CD163 (CD163 molecule)
Diseases named in the same sentence as CD163 in open-access papers (continued):
Sharing a sentence is not in itself a finding about the gene and the disease.
tumor (continued). "Contrary to our results from the tumor samples, a low density of stromal CD68+CD163− macrophages in normal tissue samples was prognostically favorable (p = 0.050), while the opposite was true for CD68+ CD163+ (p = 0.004), where a high density was favorable." (PMID 40498004, 2025). "The expression of SIRPA, LILRB1, LILRB2, Siglec1, Siglec7, Siglec9, PDCD1, CD163 and MARCO are preferentially expressed on Mono01, Mono02 and Macro03, suggesting their tumor-promoting roles." (PMID 40755770, 2025). "CD8+ and CD163+ T cells in EAC: Cytotoxic (CD8+) T-cells are innate immune cells, which recognize tumor cells by their neoantigens through T-cell receptor (TCR) and MHC-I tumor neoantigen interaction." (PMID 41369383, 2025). "Results showed a decrease in CD163+ TAMs and an increase in CD8+ T-lymphocyte infiltration into the tumor." (PMID 40918451, 2025). "By reducing the expression of M2 macrophage markers (CD163 and CD209) and suppressing the release of tumor-promoting factors such as MMP-9, RANTES, and VEGF, Deoxyschizandrin mitigates the supportive role of TAMs in tumor progression." (PMID 40330466, 2025). "M1 macrophages (CD86+CD80+) are critical for suppressing tumor growth, while M2 macrophages (CD206+CD163+) display protumor properties." (PMID 39774471, 2025). "Grade 3 adenocarcinoma regions displayed higher CD163+ M2 macrophage staining, while the infiltration of CD8+ cytotoxic T cells and MHC-II+ APCs was lower in tumor lesions (Adeno) than in adjacent normal tissue (CTL)." (PMID 41408407, 2025). "We assessed the expression of surface markers characteristic of both pro-inflammatory (CD86) and anti-inflammatory (CD163, CD206, CD209) phenotypes on macrophages cultured either in monocultures or in co-culture with tumor cells." (PMID 41009763, 2025). "Replaced suppressive CD163+ TAMs with immunostimulatory CD11chigh cells; increased CD4+/CD8+ T-cell infiltration and tumor regression." (PMID 40918451, 2025). "In parallel, the marked reduction in CD163 expression, particularly in the NPIC and M1EVs + NPIC groups, reflects a decrease in immunosuppressive TAMs, which are known to facilitate tumor progression." (PMID 40553053, 2025). "Immunostains showed that tumor cells were positive for vimentin and MUM1, and scattered tumor cells were positive for CD138 and CD163." (PMID 40161372, 2025). "The model showed strong performance in both internal and external patient groups and focused on tumor regions rich in immune cells, such as CD8+ T, CD163+ and PD-L1." (PMID 40805125, 2025). "IHC staining of post-treatment intracranial tumor sections quantified the expression of M2 macrophage markers ENO1, CD163, and phosphorylated SPHK1 (p-SPHK1)." (PMID 41353343, 2025). "While CD163 was a signature gene in our MDM population, its expression was lower in MDMs, tumor cells, and monocytes from brain versus extracranial metastases." (PMID 40954493, 2025). "Specifically, the quadruple combination showed the strongest reprogramming effects, reducing M2 markers (CD206, CD163) and increasing M1 markers (CD86, CD11c, HLA-DR) in the indirect co-culture with HCT116 cells, suggesting a shift toward anti-tumor immunity." (PMID 40160820, 2025). "They utilized TIMER and the Tumor-Immune System Interactions Database (TISIDB) to analyze the correlation between NFE2L2 and CD163, focusing on co-expressed genes in tumor-infiltrating immune cells." (PMID 40191729, 2025). "Based on the IMC findings, CD163 was included to identify most macrophages and the dual staining with CD68 supported the distinction between macrophages and tumor cells." (PMID 40601026, 2025). "As expected, given their generally relatively high abundance, αSMA+ fibroblasts, CD68+/CD163- macrophages, and CD31+/CD34+ endothelial cells were near each other, tumor cells, and T cells across all molecular subgroups examined." (PMID 39969434, 2025).
tumor (continued). "This is particularly evident in the immune cell population surrounding tumor cells, including CD4 T cells, CD8 T cells and CD163 macrophages." (PMID 39025895, 2024). "Tumors with diffuse immune infiltration and increased tumor-immune spatial interactions had higher presence of IDO1, PD-L1, PD-1 and Tim-3, while focal immune niches had more CD163 macrophages and a preliminary worse outcome." (PMID 39026018, 2024). "Among the components of the tumor immune microenvironment, the degrees of CD4 + cell and CD163 + cell infiltration and IL-6 expression in cancer tissues were significantly correlated with FDG PET/CT imaging features of primary tumors." (PMID 38627864, 2024). "EPCAM and KRT8 were abundantly expressed in tumor epithelial tissue with scattered expression of CD14 and CD163 in monocytes/macrophages." (PMID 38611120, 2024). "The treatment of HCC mouse tumor tissues with B. thetaiotaomicron and acetic acid resulted in upregulated expression of CD86 and NOS2, along with downregulated expression of CD163 and ARG1, as demonstrated by real-time PCR data and flow cytometry data." (PMID 38270111, 2024). "However, the number of CD163+ TAMs differed significantly between spatial compartments (q = 3.5 × 10−9; Benjamini–Hochberg corrected Mann–Whitney U test) with a 5.3-fold higher median count in the peritumoral stroma (5.16 ± 4.29) compared with the tumor islets (0.97 ± 0.76)." (PMID 38407373, 2024). "All of these subclusters represented M2‐like macrophages marked by the expression of CD163 and MRC1, which potentially contribute to tumour progression." (PMID 38318640, 2024). "It is worth noting that CD163 expression was not confined to macrophages but took place in malignant cells, which could be associated with epithelial-to-mesenchymal transition of the tumor cells and should contribute to the overall patient outcome." (PMID 39451197, 2024). "The AUC values, in descending order, were as follows: Tumor region CD8+PD-L1+ (95.8333%), Tumor region PD-L1 +(91.6667%), Tumor region CD8 +(93.0556%), Tumor region Foxp3+ (79.1667%), Tumor region CD163+ (77.7778%), and Tumor region CD3+Foxp3+ (77.4306%)." (PMID 38887237, 2024). "Analyzing TAM sorted via flow cytometry and assessing M2 markers (CD163, CD206, Arginase-1) through Western blot, we observed increased tumor volume and M2 marker expression in the SHP2-inhibited group." (PMID 38747738, 2024). "Further, we found that SLC7A8 + macrophages highly expressed CD163 and CD209 and other marker genes of M2 macrophages, which played a role in promoting tumor, inhibiting immune response, inducing angiogenesis and tissue repair." (PMID 38582791, 2024). "Consistent with the scRNA-seq results, FOLR2 expression was also positively correlated with TRM-related genes (CD163, MRC1, CD163L1 and LYVE1) in the whole-tumor transcriptome from the TCGA STAD database." (PMID 39702278, 2024). "We explored the potential of spatial distributions of immune cell subtypes (CD20, CD11c, CD163, ICOS, and CD8) within the tumor microenvironment to predict NMIPUC recurrence following BCG immunotherapy." (PMID 38731992, 2024). "Within the tumor core, the TAMs_0, TAMs_1, TAMs_2, and TAMs_7 subpopulations predominantly expressed M2-like macrophage markers (e.g., MRC1, IL10, and CD163), indicating an inclination towards the M2 phenotype." (PMID 38938448, 2024). "This study conducted a comparative analysis of CD163 and CD206 TAMs using digital image analysis, focusing on their spatial distribution and prognostic significance in relation to tumor-infiltrating lymphocytes (TILs)." (PMID 38893266, 2024). "TAMs are chronically polarized by the tumor and show a mixed phenotype of both anti-tumoral and pro-tumoral activation states, marked by the expression of HLA-DR and CD86 or CD163, CD206 and PD-L1, respectively." (PMID 38594506, 2024). "In the current study, the tumor that presented progression had round–oval cell predominance with abundant CD68+ and CD163+ macrophages." (PMID 39335193, 2024).
tumor (continued). "We also noticed that compared to lean patients, obese patients had more CD163+ macrophages in the TME, suggesting that dysregulated lipids in obese patients promoted macrophage tumor infiltration." (PMID 39513934, 2024). "In all these tumor types, VSIG4 expression correlated with the expression of the inhibitory macrophage marker CD163, supporting that VSIG4 is mostly expressed on suppressive macrophage populations within the tumor microenvironment." (PMID 38892347, 2024). "The immune populations of 235 PDAC patients were processed by mIHC for a panel of myeloid and lymphoid cell markers encompassing CD8+ T cells, CD4+ T cells, CD16+/CD163− (M1) macrophages and CD16+/CD163+ (M2) tumor-promoting macrophages." (PMID 38730319, 2024). "In the tumor tissues of AA patients, a significant correlation was found between CD206 and CD163, markers indicative of M2 macrophages, as opposed to iNOS, a marker for M1 macrophages." (PMID 38791954, 2024). "In comparison to ARID1A -proficient patients, patients with ARID1A deficiency exhibited a significant increase in the infiltration levels of CD8 + cells, CD163 + cells and FOXP3 + cells within the tumor tissue." (PMID 38555560, 2024). "Immunohistochemistry was used to evaluate the expression of PD-L1 and tumor microenvironment cells (CD4, CD8, CD68 and CD163)." (PMID 39123373, 2024). "Analysis revealed a close relationship between the expression of CD163, Foxp3, and ICOS in CRC tissues and tumor TNM staging." (PMID 39104717, 2024). "Selected 98 PDAC and 98 adjacent non tumor tissues as a control group were immunostained with HOXA9 and CD163 antibodies." (PMID 39462379, 2024). "We first compared the contents of M2 macrophage markers, Arg-1, IL-10, CD163, CD206, and CRNDE in tumor tissues and para-cancerous tissues." (PMID 38822362, 2024). "Regarding tumor necrosis, ANOVA analysis revealed variations in FKBP51s TME-TAMs and CD163 and CD163/FKBP51s PB-TAMs in three patient groups categorized according to the NS (0+1, 2,3)." (PMID 38651817, 2024). "PD-L1 and tumor microenvironment (CD4, CD8, CD68 and CD163) expression were investigated in LSCC using immunohistochemistry." (PMID 39123373, 2024). "After CD163+ TAM depletion, the remaining TAMs are re-educated toward the tumor-suppressing phenotype and express CD11c as well as the immune-modulatory molecules CIITA, CXCL9, and CD209D." (PMID 39516356, 2024). "In CRC, CD163+ TAMs in the invasive front correlated with epithelial-mesenchymal transition (EMT), percentage of mesenchymal circulating tumor cells, and poor prognosis." (PMID 39199574, 2024). "As expected, the vast majority of immune cell markers, such as CD163, S100A8, CD3, and FOXP3, showed higher expression levels in the TME compartment, while Ki-67, which was detected in proliferative tumor cells, was upregulated in tumor cells." (PMID 38951801, 2024). "IL-4 and IL-6 have been used to stimulate the differentiation of CD163+ M2-like TAMs from primary human monocytes, and conditioned media from these resulting TAMs increased HNC tumor cell migration, invasion, and angiogenesis in vitro." (PMID 38468824, 2024). "These TAMs express M2-phenotype markers such as CD163, CD204, and CD206, which have been shown to prevent cytotoxic T lymphocytes (CTL) infiltration into the tumor core." (PMID 38927907, 2024). "(B) Representative flow cytometry measurements of macrophage polarization: MHCII and CD86 for M1-like (anti-tumor) markers, and CD163 and CD206 for M2-like (pro-tumor) markers." (PMID 38805560, 2024). "In contrast, tumour tissue‐enriched C5‐TREM2‐Mφ and C8‐MT1H‐Mφ macrophages displayed a more anti‐inflammatory phenotype, with high expression of genes such as CD163, MARCO, and CSF1R, indicative of an M2‐like phenotype." (PMID 37994257, 2024).
tumor (continued). "The spatial immune architecture of a subset of tumors (n=30) was evaluated using multiplex immunohistochemistry (mIHC) which allowed us to determine the tumor infiltration status of CD3+, CD8+, FoxP3+, CD163+ and Ki67+ cells." (PMID 38638445, 2024). "Histologisch zeigte sich, dass der Tumor aus dicht gelagerten großen histiozytenartigen Zellen mit Expression von Vimentin, CD68 und CD163 sowie Negativität für Keratin, Langerin und SMA aufgebaut ist." (PMID 38472383, 2024). "Involving other clinical parameters such as age at diagnosis, gender, and tumor content (%) in Cox survival analysis model 2, ITGAX,SAMSN1, TNFAIP2 and CD163 showed significant values." (PMID 39015503, 2024). "Fluorescence immunostaining for the CAF marker αSMA and the M2 macrophage marker CD163 in 73 clinical CRC tumor samples allowed for quantification of αSMA-positive areas and abundance of CD163 positive cells in the tumor area." (PMID 39000110, 2024). "The lack of significant differences in cell density between the center and the margin of the tumor for CD8-, CD68-, and CD163-positive cells suggests a relatively uniform distribution of immune cells within the selected cores." (PMID 39338178, 2024). "Tumor biopsies obtained during surgery were analyzed for expression of NCF2, CYBB, CD68, CD163, and NCAM1 by RT-PCR." (PMID 38598844, 2024). "Patients with ARID1A deficiency, compared to ARID1A-proficient patients, exhibited increased infiltration levels of CD8 + P value < 0.0001), CD163 + P value < 0.001), and FOXP3 + P value < 0.001).cells within the tumor tissue." (PMID 38555560, 2024). "Immunohistochemical studies showed the co-expression of macrophage markers (CD163, CD68) and pericyte markers (NG2, MCAM) in perivascular regions of the tumor." (PMID 39796646, 2024). "Conversely, 2‐ME‐treatment resulted in fewer CD163+ cells detectable in the TME, increased levels of tumor necrosis, increased IL‐10 plasma levels, and low IL‐6 and IL‐27 plasma levels." (PMID 38600057, 2024). "CD163 + and CD206 + TAMs are particularly enriched at the tumor invasion front, correlating with vascular density, whereas CD68 + cells show no regional differences." (PMID 39068459, 2024). "The CD163+/CD206+ cluster displays a TAM M2-like phenotype and expresses markers involved in T-cell interaction and tumor progression." (PMID 39703508, 2024). "We performed immunohistochemistry analyses using FOXP3 and CD163 antibodies in the validation cohort and found very pronounced macrophage infiltration (CD163) but hardly Treg infiltration (FOXP3) into the tumor site in some samples." (PMID 39669575, 2024). "We investigated the expression of HAVCR2 and LGALS9, typical immune suppressive genes, and CD163, an M2 macrophage marker gene, and found that they were co-expressed in the macrophage clusters, indicating that the TAMs infiltrating the tumor might be M2 subtype." (PMID 39474422, 2024). "For example, chemotherapy-treated MYCN-amplified neuroblastoma patients showed increased tumor infiltration of HLA-DR+, CD11c+, CD68+, and CD14+ pro-tumorigenic macrophages that expressed immunosuppressive molecules such as Tim-3, B7-H3, and CD163." (PMID 38927907, 2024). "Immunohistochemical characterization identified these cells as CD8+, CD4+, CD20+, FOXP3+, CD163+, or CD68+ cells, and the density of each cell type in the tumor-immune microenvironment (TIME) was quantified." (PMID 39272861, 2024). "Tissues were stained for pan-cytokeratin (panCK; tumor epithelium), caspase-1, CD3 (lymphocytes), CD8 (CTL), CD68+ (monocytes/macrophages), and CD163+ (M2-like, protumoral TAMs)." (PMID 39353903, 2024). "In general, surface markers such as CD68 and CD80 show anti-tumor effects, while CD163 and CD204 show tumor-promoting effects." (PMID 39199574, 2024). "Protein expression in mouse subcutaneous tumor tissue also suggested that CD86 protein expression was increased and CD163 expression was decreased after GJB2 knockdown." (PMID 39162005, 2024).
tumor (continued). "(C) Geometric mean fluorescence intensity of anti-tumor markers (MHCII and CD86) and pro-tumor markers (CD163 and CD206) on macrophages from immuno-tumoroid cultures of CD47 knockout (KO) B16F10 cells." (PMID 38805560, 2024). "All patients with the immune-high subtype exhibited more than three immune clusters within the tumor, which were characterized by CD20-positive B cells surrounded by a high number of CD3-positive T cells, and rare cells positive for CD68 and/or CD163." (PMID 38611048, 2024). "OPN induces polarization of macrophages into M2 type, characterized by CD163, CD206 and CD209 expression, to promote tumor progression." (PMID 39062100, 2024). "CCL20 has been shown to promote CD163 expression in macrophages and induce TAM infiltration as well as M2-like macrophage polarization in tumor tissues." (PMID 39776914, 2024). "This single cell transcriptomic analysis allowed us to identify the presence of macrophages (CD163), T cells (CD3D), and pericytes (PDGFRB), as well as endothelial (VWF) and folliculostellate (SOX2) cells, within the tumor microenvironment." (PMID 39217365, 2024). "Paraffin-embedded, formalin-fixed tumour tissue blocks of 138 patients representative of the population and including early stage disease were identified, stained for CD3, CD20, CD68 and CD163 and analysed for both the stromal and intertumoral components." (PMID 38674108, 2024). "High grade tumors had a significantly higher infiltrate of FoxP3+ cells (p = 0.02), CD68+ cells (p = 0.01), CD163+ cells (p = 0.01), LAG3+ cells (p = 0.01), PD1+ cells (p = 0.01) and TIM3+ cells (p = 0.03) when compared with low grade tumours." (PMID 38691575, 2024). "Patients with severe CD163 + macrophage infiltration and increased IL-6 expression showed increased FDG uptake, metabolic volumetric parameters, and metabolic heterogeneity of tumor lesions, as well as increased FDG uptake in the BM and spleen." (PMID 38627864, 2024). "Overall, the ration of CD163+- to CD16+-monocytes was 9:1, hinting at a generally more anti-inflammatory tumor microenvironment." (PMID 38191550, 2024). "Lung and mammary tissue were obtained for immunohistochemical analysis of CD163 and CD3 expression, and histological examination was performed to analyze tumor necrosis." (PMID 38600057, 2024). "We furtherly double-stained macrophages (CD163+ CD68+), helper T cell (CD3+ CD4+), cytotoxic T cell (CD3+ CD8+), and Treg cell (CD4+ FOXP3+) of subcutaneous tumor tissues and examined the cells using immunofluorescence (IF)." (PMID 38483163, 2024). "Immunohistochemistry reveals tumor cell positivity for CD30, CD68, CD163, ALK1, ALK (D5F3), and EMA; Genetic testing shows ALK gene rearrangement in tumor cells but with different ALK fusion partners, mainly SQSTM1 (52%) and VCL (30%)." (PMID 38706599, 2024). "CD163 and CD206 TAMs only correlated with each other moderately in the stroma or tumor nest (rs = 0.493 and 0.483, respectively)." (PMID 38893266, 2024). "Histologically, the tumor was found to consist of densely clustered large histiocyte-like cells with expression of vimentin, CD68, and CD163 as well as negativity for keratin, langerin, and SMA." (PMID 38472383, 2024). "The macrophages in the invasive zone exhibited an M2-like phenotype with increased expression of CD163, MRC1, and SAAs receptor TLR2, whereas macrophages in the tumor tissue exhibited features of ECM remodeling and increased expression of MMP9 and MMP14." (PMID 37337030, 2023). "The focus of this study was to evaluate the relationships between the spatial localization and function of cell subsets distinguishable by CD68 and CD163 and their functional roles in the HNSCC tumor microenvironment." (PMID 38322012, 2023). "elucidated that PD-L1+ TAMs expressed both the pro-tumor markers CD204, CD206, and CD163, as well as the anti-tumor marker CD169, indicating that PD-L1+ TAMs have a dualistic nature." (PMID 37313405, 2023).